NSMCE1 (NSE1 component of SMC5/6 complex)
Description:
RING-type zinc finger-containing E3 ubiquitin ligase that assembles with melanoma antigen protein (MAGE) to catalyze the direct transfer of ubiquitin from E2 ubiquitin-conjugating enzyme to a specific substrate. Within MAGE-RING ubiquitin ligase complex, MAGE stimulates and specifies ubiquitin ligase activity likely through recruitment and/or stabilization of the E2 ubiquitin-conjugating enzyme at the E3:substrate complex. Involved in maintenance of genome integrity, DNA damage response and DNA repair. NSMCE3/MAGEG1 and NSMCE1 ubiquitin ligase are components of SMC5-SMC6 complex and may positively regulate homologous recombination-mediated DNA repair. MAGEF1-NSMCE1 ubiquitin ligase promotes proteasomal degradation of MMS19, a key component of the cytosolic iron-sulfur protein assembly (CIA) machinery. Down-regulation of MMS19 impairs the activity of several DNA repair and metabolism enzymes such as ERCC2/XPD, FANCJ, RTEL1 and POLD1 that require iron-sulfur clusters as cofactors.
Synonyms: NSE1
Tractability: PROTAC: UniProt records ubiquitination sites on it; ubiquitination databases record sites on it; its protein half-life has been measured.
Gene: Protein-coding gene on chromosome 16 (27,224,993 to 27,268,788, reverse strand). Ensembl gene ENSG00000169189.
Subcellular location: Nucleus; Chromosome, telomere
Subcellular location (Human Protein Atlas): Nucleoplasm; Vesicles
Pathways (Reactome):
Metabolism of proteins: SUMOylation of DNA damage response and repair proteins
Gene Ontology:
Molecular function: protein binding; protein dimerization activity; ubiquitin protein ligase activity; ubiquitin-protein transferase activity
Biological process: DNA damage response; chromatin looping; double-strand break repair via homologous recombination; protein sumoylation; regulation of telomere maintenance; DNA repair
Cellular component: nucleoplasm; nucleus; Smc5-Smc6 complex; chromosome, telomeric region; chromosome, centromeric region; mitotic spindle pole
Genetic constraint (gnomAD): Loss-of-function variants: 13 observed, 24.44 expected, observed/expected ratio (o/e) 0.53, 90% interval 0.34 to 0.85. The upper end of that interval is the gene's LOEUF score, 0.85, which puts it in group 3 of 6, group 1 being the genes least tolerant of losing a copy. Missense variants: 250 observed, 288.3 expected, observed/expected ratio (o/e) 0.87, 90% interval 0.78 to 0.96. Synonymous variants: 99 observed, 112.02 expected, observed/expected ratio (o/e) 0.88, 90% interval 0.75 to 1.04.
Homologues: Orthologues: chimpanzee NSMCE1 (99% identical), pig NSMCE1 (93% identical), rat Nsmce1 (92% identical), dog NSMCE1 (91% identical), guinea pig NSMCE1 (91% identical), mouse Nsmce1 (89% identical), macaque NSMCE1 (80% identical), tropical clawed frog nsmce1 (48% identical), zebrafish nsmce1 (39% identical), Caenorhabditis elegans nse-1 (20% identical), Drosophila melanogaster Nse1 (19% identical).
Diseases named in the same sentence as NSMCE1 in open-access papers:
NSMCE1 is named in the same sentence as 8 diseases in open-access papers, as found by Europe PMC text mining. Sharing a sentence is not in itself a finding about the gene and the disease. The quoted sentences say what the papers report.
asthma (2 papers, 2020 to 2025). "Additionally, the identified childhood-onset asthma-associated gene of JAZF1 has evidence of genetic interactions with identified genes of AHI1, NSMCE1, TDRKH, CD52, and HLA-DRB1 based on a genome-wide map of genetic interaction inferred from radiation hybrid genotypes." (PMID 32867763, 2020).
colon cancer (1 paper, 2023). "Among them, AP003555.1, ATP2B1.AS1, and NSMCE1.DT have been shown in previous studies to be closely related to colon cancer prognosis." (PMID 37629096, 2023). "Compared to normal human colonic cells (NCM460), the expression of ATP2B1.AS1 and NSMCE1.DT were higher in colonic cancer cells (including HCT116 and LoVo), while AC007728.3 exhibited a contrasting trend." (PMID 37629096, 2023). "Specifically, ATP2B1.AS1 and NSMCE1.DT exhibited higher expression in colon cancer tissues compared to noncancerous tissue, as well as higher expression in colonic cancer cell lines than in human normal cell lines." (PMID 37629096, 2023).
melanoma (1 paper, 2021). A malignant, usually aggressive tumor composed of atypical, neoplastic melanocytes. "NSMCE1 is a RING-type zinc finger-containing E3 ubiquitin ligase that assembles with melanoma antigen protein to catalyze the direct transfer of ubiquitin from E2 ubiquitin-conjugating enzyme to a specific substrate." (PMID 33663605, 2021).
tumor (1 paper, 2023). "Consistent expression trends were observed, with ATP2B1.AS1, AP003555.1, and NSMCE1.DT significantly overexpressed in tumor tissues." (PMID 37629096, 2023).
NSMCE1 also shares sentences with these, for which no sentence is quoted: breast carcinoma (1 paper); glioblastoma (1); megalencephalic leukoencephalopathy (1); prostate carcinoma (1).